AQP3 (aquaporin 3 (Gill blood group))
Diseases named in the same sentence as AQP3 in open-access papers (continued):
Sharing a sentence is not in itself a finding about the gene and the disease.
infection (15 papers, 2017 to 2025). The state of being infected such as from the introduction of a foreign agent such as serum, vaccine, antigenic substance or organism. "This aligns with their ability to upregulate key skin barrier genes, including FLG, TGM1, and AQP3, which fortify the cornified envelope to prevent water loss and infection, while boosting hydration via water and glycerol transportation." (PMID 40283895, 2025). "RNA-sequencing of infected hepatocytes revealed an increase in expression of aquaporin-3 (AQP3) and follow-up studies identified AQP3 as essential for infection and implicated it in nutrient acquisition." (PMID 35111697, 2021). "In this study, the A-allele was accompanied by increased AQP3 expression in T-cells, and increased immune cell migration and conferred resistance against infection; however, A-allele carriers were prone to graft rejection." (PMID 32521638, 2020). "The role of host aquaporins during Plasmodium infection is understood to a lesser extent, but have been implicated in blood stage infections where one report demonstrated that AQP3 localizes to the parasitophorous vacuole of P. falciparum infected red blood cells." (PMID 29775485, 2018). "In contrast, hypnozoites have a delayed recruitment of AQP3 and for several days after infection, the protein is at the PVM prominence." (PMID 32330444, 2020). "Throughout infection, AQP3 localization correlates with PvUIS4 staining in schizonts and hypnozoites." (PMID 32330444, 2020). "We observed the host AQP3 is recruited to the host-parasite interface after infection is established." (PMID 32330444, 2020). "During liver-stage infection, AQP3 localizes to the host-pathogen interface in a spatiotemporal manner that differs for actively replicating infections when compared with dormant forms." (PMID 32330444, 2020). "During the ring stage of infection, AQP3 localization was primarily observed around the periphery of the reticulocyte with small puncta associated with the PVM, while the protein appeared to be throughout the parasitophorous vacuole in schizonts." (PMID 32330444, 2020). "To test if AQP3 localizes to the PVM during the liver stage, we used immunofluorescent (IF) microscopy with antibodies targeting human AQP3 and monitored the intracellular localization of the protein throughout infection." (PMID 29775485, 2018). "Unfortunately, the complementary host preincubation study to determine auphen specificity to AQP3 is complicated by the fact that the protein is only upregulated many hours after infection." (PMID 29775485, 2018). "Among genes that were differentially expressed, aquaporin-3 (AQP3) was chosen for functional analysis because it was one of the most highly induced genes upon infection and because of previous literature related to aquaporins and parasite development." (PMID 29775485, 2018). "Our data suggest that human AQP3 is recruited to the PVM in hepatocytes to facilitate liver stage infection." (PMID 29775485, 2018). "Upon infection, AQP3 expression is induced and it is the only aquaporin isoform to be significantly (p = 1.55 x 10−7) differentially expressed." (PMID 29775485, 2018). "EPEC infection of polarized MDCK-AQP3-EGFP cells showed that AQP3-EGFP was recruited to the infection site on the apical surface." (PMID 28636623, 2017). "However, deletion of AQP3 or treatment with AQP3 inhibitor can reduce the pathogen burden in the liver and blood stage of infection." (PMID 33796134, 2021). "For instance, aquaporin 3 (AQP3), a channel which transports water, glycerol, and other small neutral molecules, undergoes an apparent alternation in oligomeric state and is recruited to the parasite upon erythrocyte infection." (PMID 33793667, 2021). "In addition to establishing a role of AQP3 in the P. vivax liver stage, we sought to determine if the protein is involved in blood-stage infections." (PMID 32330444, 2020).
infection (continued). "Regardless, our microscopy study suggests an induction of AQP3 protein expression after infection." (PMID 32330444, 2020). "Basolateral recycling plasma membrane cargoes, e.g. TfnR and AQP3, are sorted, likely by EspF and yet unidentified other effector proteins, to Rab11/Myo5b-positive apical recycling endosomes hijacked to the apical infection sites." (PMID 31242273, 2019). "However, the similarities in infection phenotypes between AQPmut cells and auphen treated cells support the targeting of host AQP3 by auphen." (PMID 29775485, 2018). "Thus, if the selectivity filter of AQP3 is unmodified by Plasmodium it could be transporting a number of small molecules throughout infection into or out of the host cytosol." (PMID 32330444, 2020). "Future work will resolve the function of AQP3 throughout infection to understand the molecules it filters to assist in parasite development, and, in doing so, could unveil additional molecular targets from which target-based radical cure drug discovery could progress." (PMID 32330444, 2020). "Additionally, to probe whether auphen acts on the host AQP3 and/or the parasite aquaporin, we pre-treated sporozoites with auphen prior to infection." (PMID 29775485, 2018). "Given the suggested involvement of AQP3 and AQP9 in infection, inflammation, and the development of disease, we investigated the contribution of these two AQPs to leukocyte phagocytosis." (PMID 40558507, 2025). "We detected AQP3 exclusively in extended membrane clusters and TVN-derived vesicles in P. vivax EEFs throughout infection, suggesting important and coincident functions." (PMID 34195101, 2021). "To further investigate AQP3 recruitment to the TVN, we analyzed P. vivax EEFs days 2–10 post-infection." (PMID 34195101, 2021). "Previous studies have shown that infection with the murine A/E pathogen C. rodentium resulted in mislocalization of the water channels aquaporin 2 and 3 (AQP2 and AQP3) from the host cell membranes to the cytoplasm." (PMID 31242273, 2019). "Further, we found no instance of AQP3 co-localizing with P. vivax TVN tubules at any day post infection despite looking in multiple planes (z-stacks)." (PMID 34195101, 2021). "At 8 dpi, AQP3 was also associated with P. vivax hypnozoites, but staining was not uniform around the PVM in every infection." (PMID 32330444, 2020). "We observed colocalization of AQP3 with Plasmodium UIS4 (upregulated in infective sporozoites gene 4), a secreted parasite protein that is incorporated to the PVM during early liver-stage infection." (PMID 32330444, 2020). "The observations that AQP3 expression is induced in response to infection and that the protein localizes to the PVM, led us to hypothesize that AQP3 is essential for Plasmodium development during the liver stage." (PMID 29775485, 2018). "In this work, we investigated the expression and involvement of AQP3 and AQP9, two aquaglyceroporins also permeable to hydrogen peroxide, in important processes of immunity such as cell migration, and the phagocytosis and killing of ingested bacteria by WBCs following infection." (PMID 40558507, 2025). "The involvement of AQP3 and AQP9 in bacterial killing was evaluated by measuring the percentage of bacterial survival at 10, 30, and 120 min of infection in the presence or not of 10 μM DFP00173 or HTS13286 or both inhibitors added together." (PMID 40558507, 2025). "There was not complete co-localization of the recruited basolateral AQP3-EGFP and localization of the apical gp135 at the infection site." (PMID 28636623, 2017). "We observed that transmembrane basolateral plasma membrane proteins not known to be involved in EPEC infection, AQP3-EGFP and the Transferrin receptor tagged with mCherry, were recruited to the infection site, where they accumulated at the EPEC microcolony." (PMID 28636623, 2017).
skin disorder (10 papers, 2015 to 2024). Any deviation from the normal structure or function of the skin or subcutaneous tissue that is manifested by a characteristic set of symptoms and signs. "Taken together, these results suggest that adapalene can partially ameliorate EGFR‐TKI‐induced skin disorders by downregulating AQP3." (PMID 38379420, 2024). "The relationship between the concentration of adapalene and skin disorders was also examined by analyzing AQP3 expression." (PMID 38379420, 2024). "It has been suggested that AQP3 upregulation is involved in keratinocyte proliferation, epidermal hyperplasia, and barrier disruption in skin disorders." (PMID 28170435, 2017). "The potential effects of the AQP-3-inducing property of this compound on proliferative skin disorders are unknown and should be investigated." (PMID 28813533, 2017).
bacterial infection (4 papers, 2017 to 2025). "Although AQP3 expression is upregulated in response to both bacterial infection model and inoculation with PBS, the presence of bacteria seemed to delay AQP3 upregulation for 24 h." (PMID 29039751, 2017). "Besides, both AQP2 and AQP3 localizations would be altered from cell membranes to cell cytoplasm after bacterial infection depending on the bacterial type III effector proteins EspF and EspG." (PMID 38089478, 2023). "Notably, the AQP3 localization shifted from its normal location along cell membranes to the cell cytoplasm during bacterial infection in C57BL/6 mice." (PMID 38089478, 2023). "However, under stress and bacterial infection (e.g., Fusobacterium) conditions, AQP1, AQP3, AQP8, and AQP10 are mainly responsible for the maintaining of water homeostasis in the gastrointestinal tract." (PMID 32565721, 2020). "No apparent involvement of individually blocked AQP3 or AQP9 was observed in the phagocytosis of K. pneumoniae by neutrophils or monocytes after 10, 30, or 60 min of bacterial infection." (PMID 40558507, 2025).
gastrointestinal disorder (2 papers, 2025). "Alterations in the expression and localization of AQPs within the gastrointestinal tract have been shown to correlate with the pathology of gastrointestinal disorders, with AQP3 being closely involved in the regulation of intestinal health." (PMID 40564302, 2025).
kidney disease (2 papers, 2022 to 2023). "Therefore, we set out to examine the effect of TAM on the expression and localization of AQP3 in collecting ducts using two different kidney disease models, namely the UUO model and the lithium-induced NDI model, which are associated with reduced AQP3 expression." (PMID 37190049, 2023).
brain diseases (1 paper, 2024). "Moreover, AQP3 is also expressed in the brain; hence, the physiological effect of magnesium sulfate on water balance observed in brain diseases could also be partly explained by the modulation of AQP3 transcripts level." (PMID 39194687, 2024).
hepatobiliary disorder (1 paper, 2025). A non-neoplastic or neoplastic disorder that affects the liver, bile ducts, and gallbladder. "Additionally, AQPs have been associated with various hepatobiliary disorders, and AQP1 and AQP4 are involved in mechanisms of reabsorption/secretion of water, but there was only a significant increase in AQP3 levels in liver tissue." (PMID 41010898, 2025).
immune disorder (1 paper, 2021). "The gene knockout mice of AQP3 have a mucosal innate immune disorder." (PMID 34796123, 2021).
AQP3 also shares sentences with these, for which no sentence is quoted: skin cancer (8 papers); chronic kidney disease (2); depression (2); Erythema (2); gastrointestinal tumors (2); helicobacter infection (2); inflammatory skin disease (2); keratoconus (2); metabolic disorders (2); acute pancreatitis (1); acute respiratory distress syndrome (1); adenocarcinoma (1); alcohol abuse (1); Bowen's diseases (1); brain tumors (1); breast tumors (1); bullous keratopathy (1); cardiac arrest (1); cataract (1); cervicitis (1); chromophobe renal cell carcinoma (1); Chronic constipation (1); chronic periodontitis (1); Cirrhosis (1); clear cell renal cell carcinoma (1); clear cell sarcoma of the kidney (1); cornea plana (1); cutaneous melanoma (1); cyst (1); cystic fibrosis (1).
A further 58 diseases each share a sentence with AQP3 in 1 paper.